BLM (BLM RecQ like helicase)
Diseases named in the same sentence as BLM in open-access papers (continued):
Sharing a sentence is not in itself a finding about the gene and the disease.
tumor (86 papers, 2001 to 2026). "BLM mutation was found to be associated with increased tumor mutation burden and more immune‐active tumor microenvironment in these patients." (PMID 38124443, 2023). "This is the first report of IFS related to BS, for which we show that both BLM alleles are maintained in the tumor and demonstrate a TPM3-NTKR1 fusion transcript in the IFS." (PMID 33219493, 2022). "On the one hand, BLM loss or mutation leads to increased genetic instability and BS development, which points to a role as a tumor suppressor." (PMID 36569948, 2022). "Recent studies have indicated that the BLM gene is the most important gene among seven high-risk PCa genes, and the high expression of BLM in PCa tissues is positively correlated with the malignant degree of the tumor." (PMID 36499126, 2022). "A study conducted on about 2000 breast tumor samples also revealed that BLM mRNA overexpression was significantly associated with high histologic grade, larger tumor size, estrogen receptor, and progesterone receptor status." (PMID 33777104, 2021). "Drp1-induced mitochondrial fragmentation, such as seen here in BLM-deficient cells, also promotes tumor growth." (PMID 33495511, 2021). "In DNA from one tumour (P034) a clear reduction of the wild-type allele compared to the normal tissue was observed, suggesting loss of the wild-type BLM allele in the tumour." (PMID 26358404, 2015). "In the tumour of one of these individuals, the BLM gene was found to be completely inactivated by somatic loss of the wild-type allele." (PMID 26358404, 2015). "Analyses of a larger group of tumours from BLM mutation carriers is needed to establish the exact molecular mechanism by which heterozygous BLM mutations initiate tumorigenesis." (PMID 26358404, 2015). "Similarly, with loss of the variant allele observed in one out of three tumours, an association of BLM with HGSOC predisposition seems unlikely, especially given the weak epidemiological data." (PMID 39794353, 2025). "Furthermore, there were two genes (FBXW7, RET) mutated exclusively in tumours and eight (BLM, GJB2, NOTCH2, NOTCH3, NTRK1, POLE, SOS1, TSC2) solely in metastases." (PMID 34572946, 2021). "We analyzed tumor DNA of six women with a BLM mutation for loss of heterozygosity." (PMID 31614901, 2019). "BLM dysfunction has been implicated in tumor development, most recently during PC tumorigenesis." (PMID 31210839, 2019). "Further knowledge on whether BLM acts as a classical tumour suppressor gene and/or whether other risk factors are necessary to initiate tumorigenesis, will allow for a more precise estimation of the CRC risk of heterozygous BLM mutation carriers." (PMID 26358404, 2015). "In addition, germline mutations in BLM are pathogenic for Bloom syndrome, an inherited disorder associated with an increased predisposition to develop many tumor types including CRC." (PMID 26318585, 2015). "In addition, since loss of BLM significantly affects lifespan and tumorigenesis, the data provide a link between error-prone end joining, genome rearrangements, and tumor formation in a model metazoan." (PMID 22183041, 2011). "This may in part be due to the highly selective nature of markers chosen for genome-wide association studies and suggests that understanding the effects of specific BLM alleles and/or associated haplotypes on tumor repression in humans will remain a future challenge." (PMID 27413734, 2016). "We hypothesized that if halving Blm gene dosage increased predisposition to tumorigenesis, overexpression would conversely decrease tumor susceptibility and consequently develop a transgenic mouse model that expresses human BLM under control of the PGK promoter (BLMTg)." (PMID 27413734, 2016). "Thus, it is possible that 2ME2, ATTM or LCS-1 treatments in BLM- or CHEK2-deficient/defective tumors may induce anti-angiogenic effects that will synergize with the SL interactions to prevent tumor vascularization while inducing SL killing." (PMID 26318585, 2015).
tumor (continued). "This work shows that in response to DNA replication stress, the Bloom’s syndrome helicase (BLM) signals to the checkpoint machinery and prevents binucleation and aneuploidy, consistent with BLM acting as tumor suppressor." (PMID 40355560, 2025). "For BLM, one of three tumours exhibited definite biallelic inactivation through loss of the wildtype allele; a second tumour had possible biallelic inactivation, with a heterozygous somatic stop-gain variant observed (phase unknown); the remaining tumour however showed loss of the variant allele." (PMID 39794353, 2025). "Hyperlactylation of BLM at Lys24 was confirmed in recurrent tumor tissues from enrolled patients through histologic analysis." (PMID 40634292, 2025). "The Bloom’s syndrome helicase BLM is essential for blocking cytokinetic abscission and preventing binucleation in response to DNA replication stress, explaining its role as a tumor suppressor." (PMID 40355560, 2025). "The ability of BLM to facilitate the degradation of the oncogene transcription factor c-Jun has been previously demonstrated, supporting the tumor-suppressing role of the BLM helicase." (PMID 40728512, 2025). "Using RNA velocity, we identified additional potential regulators of BLM tumor differentiation such as NDRG1." (PMID 38893159, 2024). "To identify other potential driver genes for BLM tumor differentiation, we computed transcriptional dynamics using RNA velocity, which identified Ndrg1 as a potential regulator of BLM tumor epithelial cell differentiation." (PMID 38893159, 2024). "Consistent with low WNT signaling in RevCSCs, BLM tumor stem cells had decreased expression of WNT/stemness-related genes compared to Min tumors such as Axin2, Id2, Sox4, Wnt6, Wnt10a, Id3, Prox1, and Id1." (PMID 38893159, 2024). "In our cohort, 34.48% (22/64) of patients exhibited positive PD-L1 expression in tumor cells, and this expression was associated with GAs in CTNNB1 and BLM." (PMID 38439030, 2024). "Because tumor stem cells of BLM tumors showed increased expression of Cdx2, we focused on CDX2 as a potential regulator of BLM tumor differentiation." (PMID 38893159, 2024). "In order to verify the oncogenic capacity of circ_0001671 via the miR-27b-3p/BLM axis in an in vivo context, a xenograft tumor model was established in nude mice." (PMID 38806577, 2024). "Expression patterns of circ_0001671, BLM, and miR-27b-3p in PCa tumor tissue and adjacent normal tissue were subsequently assessed by quantitative PCR." (PMID 38806577, 2024). "Our RNA velocity analysis suggested Ndrg1 as a potential additional driver for BLM tumor differentiation." (PMID 38893159, 2024). "Among the upregulated genes were BRCA2 and BLM, also with demonstrated roles in suppression of tumor progression." (PMID 39138582, 2024). "In contrast, in addition to Clu and Ly6a, the tumor stem cell population of BLM tumors had significant upregulation of differentiation-related genes such as Guca2a, Car1, Cdx2, Car2, and Muc2." (PMID 38893159, 2024). "The role of CDX2 and NDRG1 as putative regulators for BLM tumor cell differentiation was verified using organoids derived from BLM tumors." (PMID 38893159, 2024). "We also identified additional potential regulators of BLM epithelial tumor differentiation such as CDX2 and NDRG1." (PMID 38893159, 2024). "Knockdown of BLM inhibits PCa cell proliferation and promotes apoptosis, and overexpression can reverse tumor growth inhibition." (PMID 37251536, 2023). "To assess the potential role of BLM in mediating the anti-tumor sensitivity to olaparib, we silenced BLM expression using shRNA and evaluated the growth of PC3 cells in the presence of olaparib." (PMID 37415147, 2023). "ML216 is a selective inhibitor of tumor cell growth that effectively impairs the function of BLM in human cells." (PMID 37415147, 2023). "In most cases, strong BLM positivity was present in the tumour tissue whereas BLM staining in the normal brains was barely detectable." (PMID 37169803, 2023).
tumor (continued). "This is also possible because within the BLM gene, resides the RecQ homologs, in particular, the RecQL4 helicase acts as a tumor suppressor." (PMID 37796556, 2023). "In this study, we first evaluated the expression levels of BLM in both PCa tumor tissues and cell lines." (PMID 37415147, 2023). "Together with other RECq helicase family members, BLM is considered a tumor suppressor that finely regulates chromosomal stability at the telomeric and centromeric level during critical phases (DNA crosslink and DNA replication fork arrest) of DNA replication." (PMID 35495117, 2022). "Previously, it has been shown that BLM acts as a tumor suppressor since it prevents crossover between homologous chromosomes." (PMID 35267530, 2022). "These authors report that BLM has a dual function both as a tumour suppressor and possibly as a proto-oncogene, being probably involved in the mechanisms of its deregulation in tumours." (PMID 36177351, 2022). "Post-translational modification (PTM) of BLM is important for its function in DNA repair and tumor radiosensitivity." (PMID 34606619, 2021). "Perhaps a more pertinent query will also be—when does BLM act as a tumor suppressor and when does it convert into a proto-oncogene?" (PMID 33777104, 2021). "POLE, BLM, ARID1A and APC genes were mutated within a tumor that originated within the temporal lobe, but for this gene the highest expression was in the midline structures as opposed to temporal lobe." (PMID 34257334, 2021). "It is also possible that a single or combination of yet undiscovered PTM on BLM acts like a trigger that converts BLM from a tumor suppressor into an oncogene." (PMID 33777104, 2021). "We also analyzed the xenografts tumour tissues and found that the BLM level is higher in the USP37 WT tumors compare with USP37 S114A tumors." (PMID 34606619, 2021). "Meanwhile, in the cell and tissue levels, we clarified the expression of the real hub gene, and the results further confirmed that BLM possesses completely different expression patterns in CCA compared with the non-tumor control." (PMID 33828983, 2021). "Whereas BARD1, BLM, and RAD51D mutations have a possible ethnic association, we identified only partial support for tumor and family member associations due to the limited sample size." (PMID 32566746, 2020). "One XB type tumour (YOPC31) had mutations in the DNA damage pathway (RAD50, RAD51, BLM and BRD7), with the highest mutational burden (6.24 mutations/Mb), but the TIDE score of this tumour indicated lower responsiveness to anti-PD-1/PD-L1 therapy." (PMID 32235905, 2020). "In general, there was a statistically significant and ~10-fold decrease in the relative size of all BLM- and CHEK2-deficient tumor spheres treated with 2ME2, ATTM and LCS-1 relative to controls." (PMID 26318585, 2015). "Collectively, these data indicate that 2ME2, ATTM, and LCS-1 treatments decrease the total number of BLM- and CHEK2-deficient colonies, and also the sizes of 3D tumor spheres, suggesting each is a strong lead candidate therapeutic compound." (PMID 26318585, 2015). "G2-synchronized HeLa tumor cells show a strongly reduced pKAP-1 level at 4 h post IR compared with unsynchronized cells which is fully or partly restored after CtIP or BLM depletion." (PMID 23935532, 2013). "We conclude that BLM is a proliferation marker in normal and neoplastic cells in vivo, and, as a consequence, is expressed at a higher level in tumours than in normal quiescent tissues." (PMID 11461087, 2001). "Here, we have analysed the distribution of BLM in normal and tumour tissues from humans using a recently characterized, specific monoclonal antibody." (PMID 11461087, 2001). "In contrast, expression of BLM was observed in a variety of tumours of both lymphoid and epithelial origin." (PMID 11461087, 2001).
tumor (continued). "In order to maintain genomic stability in both healthy and tumor tissues, phosphorylated BLM may subsequently interact with Polo-like kinase 1 via its polo-box domain." (PMID 36499126, 2022). "Thus, inhibiting BLM would also affect ribosome biogenesis, which is known to be of particular importance for fast-proliferating cells such as tumor cells." (PMID 36569948, 2022). "It has been proposed that BLM can act both as a tumor suppressor and as a proto-oncogene." (PMID 36569948, 2022). "BLM, as a member of the RecQ-like helicase family, plays an important role in cellular metabolism such as DNA replication, recombination, transcription, repair, and telomere maintenance, which overexpressed in the tumor cell." (PMID 33540684, 2021). "BLM has been proposed to act as a tumor suppressor by preventing crossovers between homologous chromosomes, which could lead to loss-of-heterozygosity." (PMID 33500419, 2021). "Furthermore, the expression pattern of BLM in both the eCCA data set GSE132305 and the iCCA data set GSE76297 suggested that the expression of BLM in tumor tissue was enhanced compared with paracancerous samples." (PMID 33828983, 2021). "Thus, in mice, BLM acts as a factor essential for maintaining genomic stability and is involved in the prevention or reduction of tumor development." (PMID 33777104, 2021). "While a large number of studies have implicated AKT and PRAS40 hyperactivity in promoting tumor cell proliferation, the correlation between these signaling molecules and BLM has not been previously reported." (PMID 31210839, 2019). "Therefore, we analysed four available tumours and matched normal colonic tissue for loss of heterozygosity (LOH) and mutations in the BLM locus." (PMID 26358404, 2015). "We further show that three chemicals predicted to functionally substitute for SOD1 silencing also induce preferential killing within BLM- and CHEK2-deficient cells in short (5-day), moderate (14-day) and long-term (28-days) assays in both 2D culture and 3D tumor models." (PMID 26318585, 2015). "In contrast, a subset of genes including tumor suppressors, such as BRCA1, BARD1 and BLM, were highly deregulated by loss of Spt6 but were only modestly affected or unaffected by loss of PAAF1, even though Spt6 level in these cells was significantly diminished." (PMID 22316138, 2012). "However, viable BLM-null mice were generated with the removal of neomycin plasmid sequence, of which 30% of these mice presented with a wide spectrum of spontaneous tumours." (PMID 23036272, 2012). "Furthermore, BLM was one of the lactylated proteins enriched in the tumor resistance pathway." (PMID 40634292, 2025). "While many early important findings came from in vitro studies and cell-based experiments, investigating the function of the BLM gene in a complex organism could help elucidate the disease phenotype observed in BS and clarify its paradoxical role in tumor suppression or promotion." (PMID 40728512, 2025). "Importantly, ablation of BLM rescued tumor growth even in presence of both C17 and CPT." (PMID 38421735, 2024). "We could observe that BRCA1 and BLM were also expressed higher in high-CDK2 tumours." (PMID 38732271, 2024). "Although there are contradictory reports suggesting the roles of BLM as tumor suppressor versus oncogenic driver, it is likely that proper BLM expression (no higher or lower expression) is required for genome stability and any disruption to that balance could lead to tumorigenesis." (PMID 35267530, 2022). "Hence, these characteristics point toward BLM being a tumor suppressor." (PMID 33777104, 2021). "Finally, after a range of screening and validation tests, we identified a bloom syndrome helicase (BLM) gene that could indeed promote the tumor progression and predict the prognosis of CCA." (PMID 33828983, 2021).
tumor (continued). "Given that AKT (Ser473) and PRAS40 (Thr246) phosphorylation also influence tumor growth-related ROS production, we assessed the link between BLM expression and ROS production in these cells, revealing that ROS production was significantly increased upon BLM downregulation." (PMID 31210839, 2019). "Importantly, BC arising in CHEK2, NBN/NBS1 and BLM heterozygotes usually demonstrates retention of the wild-type allele in the tumor, therefore there is no ground to expect selective chemosensitivity in these tumor types." (PMID 27555886, 2016). "RECQL4 is a member of a family of DNA helicases including Bloom (BLM) and Werner (WRN) helicases, All three members are associated with familial cancer predisposition syndromes with high frequencies of mesenchymal derived tumours, with RTS in particular developing OS at approximately 30% frequency." (PMID 23036272, 2012). "Hence BLM acts as a sensor, transmitter and finally the effector at different steps during the entire DNA damage signaling cascade - effectively acting as the "caretaker tumor suppressor"." (PMID 21050475, 2010). "Hence BLM seems to be a protein involved in multiple functions - all of which may together contribute to its reported role as a "caretaker tumor suppressor"." (PMID 21050475, 2010). "Since BLM plays an important role in regulating both replication stress and telomere synthesis in ALT, which has revealed its vulnerabilities in ALT tumor therapy." (PMID 40025590, 2025). "Through immunohistochemical assay, elevated levels of BLM, Ki-67, and PCNA were observed in the tumor tissues with circ_0001671 overexpression when compared to those in the control group." (PMID 38806577, 2024). "Expression of GFP-BLM (aa 181–212) augmented the rate of tumorigenesis, indicating that the 32–amino acid stretch in BLM that interacted with RAD54 promoted tumor growth, even in the presence of the chemotherapeutic drug CPT." (PMID 38421735, 2024). "Therefore, there is a possible indication that BLM may act as a tumor suppressor." (PMID 37796556, 2023). "We performed IHC analysis on 90 paraffin-embedded PCa tumor tissues and their adjacent normal tissues (ANT) to evaluate BLM expression." (PMID 37415147, 2023). "In recent decade, many tumor-suppressor genes such as BRCA1, BRCA2 and BLM and downstream nucleases including XPF and MRE11 have been suggested as proteins that are important for R-loop tolerance and removal." (PMID 33857133, 2021). "This resulted in high levels of BLM expression, which mis-localized to the cytoplasm due to which a heightened DDR was seen in the tumor samples." (PMID 33777104, 2021). "Subsequent genome-wide profiling of this tumour showed that multiple regions exhibited copy-number neutral LOH, including the entire q-arm of chromosome 15 on which the BLM gene is located." (PMID 26358404, 2015). "For example, BLM and CHEK2 are somatically altered in a number of tumor types including CRC, and normally function within the homology directed repair (HDR) pathway (“error-proof” DSB repair pathway)." (PMID 26318585, 2015). "BLM and CHEK2 are two evolutionarily conserved genes that are somatically altered in a number of tumor types." (PMID 26318585, 2015).